EMP2 (epithelial membrane protein 2)
Diseases named in the same sentence as EMP2 in open-access papers (continued):
Sharing a sentence is not in itself a finding about the gene and the disease.
nasopharyngeal carcinoma (6 papers, 2015 to 2025). A carcinoma arising from the nasopharyngeal epithelium. "Conversely, in urinary bladder urothelial carcinoma, cutaneous melanoma, nasopharyngeal cancer, and B-cell lymphoma, EMP2 overexpression suppresses the viability and proliferation of cancer cells, functioning as a tumor suppressor." (PMID 39866225, 2025). "The lncRNA nuclear enriched abundant transcript 1 (NEAT1) can affect EMP2 expression via miR-101-3p and slow the progression of nasopharyngeal carcinoma." (PMID 36217151, 2022). "EMP2 can induce apoptosis in the CNE-2 nasopharyngeal carcinoma cell line and expose cells to radiotherapy." (PMID 36217151, 2022). "Similar to nasopharyngeal cancer, EMP2 has been discovered to act as a novel biomarker to suppress cutaneous melanoma." (PMID 31652725, 2019). "In nasopharyngeal carcinoma, EMP2 can exist as a tumor suppressor." (PMID 36217151, 2022). "In line with the role of EMP2 in nasopharyngeal cancer and melanoma, EMP2 overexpression inhibited cell proliferation, migration, and invasion and caused G1 cell cycle arrest, while downregulation of EMP2 by siRNA resulted in an enhanced cell migratory ability." (PMID 33799364, 2021). "EMP2 possesses anti-tumor properties by suppressing the growth of nasopharyngeal carcinoma cells." (PMID 31652725, 2019). "In lung cancer and nasopharyngeal carcinoma cells, only a low level of EMP2expression is detected, which can impact lung cancer cell metastasis and nasopharyngeal carcinoma cell death, indicating that EMP2 might present a tumor suppressor gene role in these two tumors." (PMID 36217151, 2022). "In this study, we found that a high EMP2 protein level could be an independent prognostic factor for DSS in UBUC patients, suggesting that loss of EMP2 expression plays a crucial role in the mortality of UBUC, similar to its role in nasopharyngeal carcinoma and UTUC observed in our earlier studies." (PMID 25940704, 2015). "In nasopharyngeal carcinoma, EMP2 expression is generally weak or absent in tumor tissues but moderate to strong in adjacent non-tumor tissues, with higher levels of EMP2 associated with significantly longer survival times." (PMID 39866225, 2025).
lung carcinoma (5 papers, 2021 to 2025). "Only a few studies have shown that the low EMP2 expression might be closely associated with the poor prognosis and malignant metastasis of lung cancer." (PMID 36217151, 2022). "Taken together, these findings indicate that FK002-exatecan of EMP2 has effective antitumor activity against lung cancer, especially lung squamous cell carcinoma." (PMID 41173824, 2025). "To evaluate the effect of EMP2 on lung cancer cells, we performed cell proliferation, clonal formation, and migration assays in wild-type and EMP2-overexpressing lung cancer cells." (PMID 41173824, 2025). "The results showed that EMP2 had limited effects on the proliferation, clonal formation, and migration of lung cancer cells." (PMID 41173824, 2025). "And based on this, we constructed a novel ADC specifically targeting to kill EMP2-highly expressed lung cancer." (PMID 41173824, 2025). "Our data suggest that EMP2 is more frequently expressed in squamous lung cancer than other pathologic types of lung cancer." (PMID 41173824, 2025). "We provide one of the first examples of ADCs targeting EMP2, offering a novel strategy for lung cancer therapy." (PMID 41173824, 2025). "This study identifies EMP2 as a novel molecular target for lung cancer therapy and establishes a foundation for developing ADCs that selectively eradicate lung cancer cells." (PMID 41173824, 2025). "Next, we evaluated the antitumor activity of FK002-exatecan of EMP2 in a series of lung cancer models in vivo." (PMID 41173824, 2025). "To evaluate the cytotoxicity of FK002-exatecan in vitro, we screened lung cancer cell lines with high EMP2 expression by immunoblotting." (PMID 41173824, 2025). "The two signatures show an overlap of four genes (EMP2, AGER, STX11, GYPE) with two of them known to be linked to lung carcinoma." (PMID 38993634, 2024). "In addition, by tunel staining, we found that FK002-exatecan effectively induces apoptosis of lung cancer cells with high EMP2 expression." (PMID 41173824, 2025). "However, there is still a short functional study on the effects and mechanisms of EMP2 in lung cancer." (PMID 36217151, 2022). "The association between EMP2 and miRNAs in the development of human cancer, particularly in lung cancer, is not yet well elucidated." (PMID 33799364, 2021). "Therefore, low EMP2 levels in lung cancer might be an essential factor in the physical properties of lung cancer cells' migration and invasion." (PMID 36217151, 2022). "We employed wild-type and EMP2-overexpressing lung cancer cells, including A549, H520, NCI-H1703, and lung cancer cell lines with high EMP2 expression, NCI-H226 and SK-MES-1, to test the cytotoxicity of FK002-exatecan." (PMID 41173824, 2025). "In our study, by using a tissue-microarray-based screening of an antibody library, we developed the EMP2-directed ADC, FK002-exatecan, which induced tumor eradication in several lung cancer cell lines and xenograft mouse models." (PMID 41173824, 2025). "FK002-exatecan induced apoptosis in lung cancer cells with high EMP2 expression compared to the negative control." (PMID 41173824, 2025). "Recent research has found that tissue-specific human EMP2 is highly expressed in lung tissue but not in lung cancer tissues." (PMID 36217151, 2022). "Dysregulated expression of EMP2 was observed in various cancers, but its role in human lung cancer is not yet clarified." (PMID 33799364, 2021).
endometrial adenocarcinoma (4 papers, 2008 to 2013). "Moreover, dysregulation of EMP2 has been linked to endometrial adenocarcinoma, where upregulation of EMP2 is a prognostic indicator of advanced or high grade disease." (PMID 18400107, 2008). "Example of the REMARK profile illustrated using data from a study of expression of epithelial membrane protein-2 in patients with endometrial adenocarcinoma." (PMID 22642691, 2012). "EMP2 is necessary for blastocyst implantation in mice, and aberrant EMP2 expression correlated with poor survival in endometrial adenocarcinoma patients." (PMID 18400107, 2008). "In addition, high levels of EMP2 are seen in representative example of endometrial adenocarcinoma." (PMID 22585360, 2013). "The tetraspan protein epithelial membrane protein-2 (EMP2), which mediates surface display of diverse proteins, is required for endometrial competence in blastocyst implantation, and is uniquely correlated with poor survival from endometrial adenocarcinoma tumors." (PMID 18400107, 2008).
glioma (4 papers, 2020 to 2025). A benign or malignant brain and spinal cord tumor that arises from glial cells (astrocytes, oligodendrocytes, ependymal cells). "Accumulating evidence suggests that EWSR1-induced circNEIL3/IGF2BP3 enhances glioma progression by regulating macrophage polarization and circRNA-0002109 enhances glioma malignant progresses by regulating the miR-129-5P/EMP2 axis." (PMID 37540226, 2023). "Lastly, we find an association between areas of vascular proliferation and EMP2 expression, suggesting increased utilization of EMP2 in glioma cells surrounding areas of angiogenesis." (PMID 33063013, 2020). "Tissue microarrays indicate that EMP2 levels are significantly lower in low-grade gliomas than in high-grade gliomas; however, in GBM patients, EMP2 expression does not significantly impact survival times." (PMID 39866225, 2025).
melanoma (4 papers, 2018 to 2025). A malignant, usually aggressive tumor composed of atypical, neoplastic melanocytes. "For instance, MEF2A, EMP2, ZNF440, PIGL, FRMD4B, and HIF3A are not only downregulated in TCGA-SKCM melanoma samples but also essential for restraining tumor growth in CRIPSR KO screens." (PMID 37904237, 2023). "EMP2’s role in cancer varies markedly across different types; it acts as a tumor suppressor gene in cancers like B-cell lymphoma and melanoma, where it is often downregulated or absent." (PMID 39866225, 2025).
B-cell lymphoma (3 papers, 2006 to 2025). "One example is the EMP2 gene, which encodes a tetra-span membrane protein that has been reported to suppress B-cell lymphoma tumorigenicity." (PMID 16729877, 2006). "Except for epithelial cells, suppression subtractive hybridization has isolated the mouse ortholog Emp2, which suppresses B cell lymphoma tumorigenicity via a functional tumor suppressor phenotype." (PMID 25940704, 2015).
invasive breast carcinoma (3 papers, 2017 to 2025). A carcinoma that infiltrates the breast parenchyma. "Studies have indicated heightened EMP2 protein levels in 63% of invasive breast cancer and 73% of triple-negative tumors." (PMID 41173824, 2025). "EMP2 is aberrantly upregulated in multiple human cancers, including 63% of invasive breast cancers." (PMID 34869721, 2021).
ovarian carcinoma (3 papers, 2011 to 2022). A malignant neoplasm originating from the surface ovarian epithelium. "In an ovarian cancer transplanted tumor model, anti EMP2 divalent antibody therapy reduces ovarian cancer cell proliferation and promotes apoptosis in vivo." (PMID 36217151, 2022). "In conclusion, EMP2 is novel cancer biomarker, notably for endometrial and ovarian cancer, that has been previously shown to be an independent prognostic indicator, and an effective target in preclinical recombinant antibody therapy." (PMID 22585360, 2013). "A panel of six genes: CCNE2, DKFZp1312, PPIC, EMP2, MAL2 and SLC6A8 may serve as potential markers for CTC derived from breast, endometrial, cervical, and ovarian cancers." (PMID 21827674, 2011).
urinary bladder urothelial carcinoma (3 papers, 2015 to 2022). "EMP2 might also be a tumor suppressor in bladder urothelial carcinoma (BLCA)." (PMID 36217151, 2022). "In the urinary bladder urothelial carcinoma, CREB1 also plays a tumor suppressor role by transactivating epithelial membrane protein 2 (EMP2)." (PMID 27801665, 2016).
diabetic retinopathy (2 papers, 2022). "MRs obtained in this study might serve as potential biomarkers for EMP2 induced lesion under hypoxia, illustrating gene expression landscapes which might be specific for diabetic retinopathy and might provide improved understanding of the disease." (PMID 35799115, 2022). "This study supports further investigation of EMP2 as a therapeutic target for retinal neovascularization in diseases such as age-related macular degeneration (AMD), retinopathy of prematurity, and diabetic retinopathy." (PMID 36371458, 2022).
endometrial tumor (2 papers, 2013 to 2021). "In this study, we characterize a residualizing imaging agent, a 64Cu-labeled minibody to EMP2, and demonstrate its effectiveness in imaging human EMP2-positive endometrial tumor xenografts." (PMID 22585360, 2013). "Small animal PET imaging showed excellent tumor targeting of the 64Cu-DOTA-minibody in mice bearing EMP2 positive endometrial tumor xenografts." (PMID 22585360, 2013). "EMP2 promotes endometrial tumor formation and migration through activation of the FAK/Src pathway." (PMID 33799364, 2021). "Following conjugation to DOTA (1,4,7,10-tetraazacyclododecane-N,N′,N′,N′′′-tetraacetic acid), the minibody was radiolabeled with 64Cu (t1/2 = 12.7 h) and evaluated in mice as a positron emission tomography (PET) imaging agent for human EMP2-expressing endometrial tumor xenografts." (PMID 22585360, 2013). "Thus, whole-body PET detection of this anti-EMP2 antibody fragment may have promise as a potential imaging agent for staging and monitoring of EMP2-positive endometrial tumors." (PMID 22585360, 2013).
gynecologic cancers (2 papers, 2013 to 2019). "In gynecologic cancers, approximately 70% of serous and endometrioid ovarian tumors express higher levels of EMP2 protein." (PMID 31652725, 2019). "EMP2 is a tetraspan protein that is upregulated in a number of gynecological cancers, including endometrial and ovarian." (PMID 22585360, 2013).
nephrotic syndrome (2 papers, 2018 to 2019). A collection of symptoms that include severe edema, proteinuria, and hypoalbuminemia; it is indicative of renal dysfunction. "Epithelial membrane protein 2 (EMP2) mutations were identified in patients with childhood onset autosomal recessive SSNS and two Turkish siblings with mutations were reported to have steroid-responsive but frequently relapsing nephrotic syndrome." (PMID 29594119, 2018).
non-small cell lung carcinoma (2 papers, 2021). A group of at least three distinct histological types of lung cancer, including non-small cell squamous cell carcinoma, adenocarcinoma, and large cell carcinoma. "In this study, we analyzed the expression of EMP1-3 and investigated the biological function of EMP2 in non-small cell lung cancer (NSCLC)." (PMID 33799364, 2021). "EMP2 also suppresses non-small cell lung cancer cell growth by inhibition of MAPK pathway." (PMID 34869721, 2021).
phyllodes tumor (2 papers, 2020 to 2023). A benign, borderline, or malignant fibroepithelial neoplasm arising from the breast and rarely the prostate gland. "With increasing histologic grade, the expression of EMP1, EMP2, and EMP3 decreases in the epithelial component and increases in the stromal component of phyllodes tumors." (PMID 37008256, 2023). "Univariate analysis of the impact of EMP1, EMP2, and EMP3 expression in phyllodes tumors." (PMID 32857809, 2020).
bacterial pneumonia (1 paper, 2021). Acute infection of the lung parenchyma caused by bacteria (e.g., Streptococcus pneumoniae, Haemophilus influenzae, Chlamydia pneumoniae, Mycoplasma pneumoniae, and Legionella pneumophila). "During bacterial pneumonia in mice, knockout of EMP2 attenuated neutrophilic lung injury and improved survival." (PMID 34869721, 2021).
bladder cancer (1 paper, 2024). "Specifically, EMP2 was recently shown to be implicated in G2/M cell cycle arrest through regulation of the G2/M checkpoint in vitro in bladder cancer, an observation that aligns well with the downregulation of EMP2 along with the G2/M arrest effects in our study." (PMID 39456519, 2024).
breast malignant phyllodes tumors (1 paper, 2025). "In breast malignant phyllodes tumors, EMP2 is downregulated in epithelial cells but upregulated in stromal components." (PMID 39866225, 2025).
breast phyllodes tumor (1 paper, 2020). A benign, malignant, or borderline circumscribed biphasic neoplasm that arises from the breast. "In this study, we aimed to evaluate the expression of EMP1, EMP2, and EMP3 in breast phyllodes tumors (PTs), and to investigate their clinical implications." (PMID 32857809, 2020).
chronic kidney disease (1 paper, 2019). Impairment of the renal function secondary to chronic kidney damage persisting for three or more months. "Additionally, in a whole-exome sequencing of 3,315 patients with chronic kidney disease, only two individuals were found to have heterozygous variants of in EMP2 of unclear significance, and these mutations were deemed unlikely related to their underlying kidney disease." (PMID 31508419, 2019).
Cirrhosis (1 paper, 2025). A chronic disorder of the liver in which liver tissue becomes scarred and is partially replaced by regenerative nodules and fibrotic tissue resulting in loss of liver function. "Bioinformatics and immunohistochemical analysis consistently demonstrate that EMP2 expression increases as the disease progresses from hepatitis to cirrhosis and ultimately to HCC." (PMID 39866225, 2025).
congenital nephrosis (1 paper, 2019). "Since mutations in the human EMP2 gene have been previously linked to hereditary congenital nephrosis in a small subset of patients, we analyzed Emp2 null mutant mice for signs of proteinuric kidney disease and glomerular defects." (PMID 31508419, 2019).
COVID-19 (1 paper, 2023). A disease caused by infection with severe acute respiratory syndrome coronavirus 2. "Several of these genes (PELI1, MAP3K8, LAMA3, EMP2, CTNNAL1, CAV1, LRRK2, SFRP4) may also be involved in lung fibrosis, a severe complication of COVID-19." (PMID 37561814, 2023).
diabetes (1 paper, 2019). "This is supported by a recent study implicating Emp2 in a maladaptive pathway of vSMC proliferation in diabetic rats and raises the possibility of targeting EMP2 for the treatment of vasculo-proliferative diseases in diabetes." (PMID 31508419, 2019).
hepatocellular carcinoma (1 paper, 2025). A malignant tumor that arises from hepatocytes. "Through a comparative analysis of gene expression data from hepatocellular carcinoma samples with high vs. low EMP2 expression, we identified 28 genes associated with autophagy, such as IGFBP2 and BNIP3, suggesting a potential linkage between EMP2 and autophagy in liver cancer." (PMID 39866225, 2025). "We conducted immunohistochemical analyses to explore the expression patterns of EMP2 protein across various stages of liver disease, ranging from normal liver tissue to hepatocellular carcinoma, using a comprehensive liver disease tissue microarray." (PMID 39866225, 2025). "To investigate the expression patterns of EMP1, EMP2, and EMP3 in hepatocellular carcinoma (HCC) and normal liver tissues, we analyzed mRNA expression data from 374 HCC patients obtained from The TCGA database." (PMID 39866225, 2025).
Infertility (1 paper, 2008). "If EMP2 expression is an important physiologic switch for implantation competence, this implies that infertility in some cases may be due to genetic or biologic impairments in the program of endometrial EMP2 expression." (PMID 18400107, 2008).
liver cancer (1 paper, 2025). An epithelial or non-epithelial malignant neoplasm that arises from the liver. "This study aimed to investigate the expression level, biological functions, and molecular mechanisms of EMP2 in liver cancer." (PMID 39866225, 2025). "This study is the first to explore EMP2’s expression, biological function, and molecular mechanisms in liver cancer, particularly focusing on the interaction between autophagy in liver cancer cells and EMP2-mediated integrin activation." (PMID 39866225, 2025). "Our analysis of transcriptome data from 374 liver cancer patients from the TCGA database revealed that only EMP2 shows significant differences in expression between liver cancer and normal liver tissues, suggesting its significant role in the onset of liver cancer." (PMID 39866225, 2025). "In addition, the level of EMP2 protein expression was assessed in various liver or liver cancer cell lines." (PMID 39866225, 2025). "Therefore, we hypothesize that EMP2 could play a significant role in the invasion and metastasis of liver cancer cells." (PMID 39866225, 2025). "Our study also found that EMP2 downregulation led to a significant reduction in ITGA5 protein expression, weakening the invasion ability of liver cancer cells and resulting in fewer and smaller experimental lung metastases; conversely, overexpression had the opposite effect." (PMID 39866225, 2025).
liver cirrhosis (1 paper, 2025). "The experimental results demonstrated an increasing trend in EMP2 protein expression as liver disease progressed from inflammation to liver cirrhosis and ultimately to HCC." (PMID 39866225, 2025).
liver diseases (1 paper, 2025). "Immunohistochemical staining was performed to evaluate the expression level of EMP2 protein in liver disease tissue microarrays." (PMID 39866225, 2025). "Moreover, the expression level of EMP2 protein in HCC tissue positively correlated with the malignancy grade, indicating a significant role of EMP2 in the progression of liver diseases." (PMID 39866225, 2025).
lung adenocarcinoma (1 paper, 2021). A carcinoma that arises from the lung and is characterized by the presence of malignant glandular epithelial cells. "For the lung adenocarcinoma cell line H1299, reduced phosphorylated (p-) AKT and p-p38 were found in the EMP2 transfectants, while the expression level of p-ERK1/2 was enhanced compared to mock cells." (PMID 33799364, 2021).